CRP (C-reactive protein)
Diseases named in the same sentence as CRP in open-access papers (continued):
Sharing a sentence is not in itself a finding about the gene and the disease.
Obesity (continued). "A study investigating the relationship between obesity and disease activity in AS patients found that obese individuals had higher CRP levels, increased disease activity, and more pronounced radiographic damage." (PMID 41578780, 2025). "Obesity is a primary driver of elevated CRP due to adipose-derived pro-inflammatory cytokines like IL-6." (PMID 40566547, 2025). "This study underscores the utility of salivary CRP as a noninvasive biomarker for obesity‐related inflammation." (PMID 40547317, 2025). "CRP level is an important indicator of subclinical systemic inflammation in individuals with severe obesity." (PMID 39746069, 2025). "Of particular note, inflammatory markers leptin and hs-CRP showed strong positive associations with CIMT (p < 0.001), underscoring the role of chronic low-grade inflammation in obesity-induced endothelial dysfunction." (PMID 40940402, 2025). "Hs-CRP was found to be almost twice higher in the obesity group than in the control/overweight group; however, the difference was found to be marginally non-significant (0.36 vs. 0.20 mg/dL, p = 0.076)." (PMID 40868054, 2025). "Women with overweight (P-value<0.001) or obesity (P-value<0.001) versus women with healthy weight, and women who had ever versus never used hormonal contraception had higher concentrations of CRP (P-value = 0.01)." (PMID 40920854, 2025). "Results showed that insulin, CRP, and adiponectin play an important role in differentiating patients diagnosed with obesity and intermediate hyperglycemia." (PMID 40282897, 2025). "Perimenopausal women with overweight or obesity (BMI ≥ 25 kg/m2) showed significantly higher levels of glucose, insulin resistance indices, IL-6, and CRP, confirming the contribution of excess body weight to low-grade systemic inflammation." (PMID 40944273, 2025). "Apart from acute stages of inflammation resulting e.g. from infections, elevated levels of CRP and IL-6 are also observed in a condition coined as low-grade inflammation such as obesity." (PMID 39899498, 2025). "Collectively, the reciprocal shift from protective proteins like TTR, APOD, and PRDX2 to pro-inflammatory mediators such as CRP and C9 highlights a coordinated reprogramming of adiposome cargo in obesity." (PMID 40981199, 2025). "Patients aged 56 years or older (p = 0.0086), those with low hemoglobin (p = 0.0052), obesity (p < 0.0001), or elevated CRP levels (p < 0.0001) had significantly reduced survival and a higher likelihood of requiring ventilation." (PMID 40860652, 2025). "Elevated IL-6 and CRP levels are common in obesity, and although direct evidence linking GCKR variants to obesity is limited, this pathway warrants further investigation." (PMID 41150798, 2025). "Our findings suggest that MHR outperforms traditional markers like hs-CRP and WBC in predicting obesity-associated cardiac dysfunction." (PMID 40432213, 2025). "In response to elevated IL-6 levels, the liver triggers the secretion of high-sensitivity C-reactive protein (hs-CRP), a key marker of inflammation in obesity." (PMID 40564199, 2025). "While other studies have considered BMI in a comprehensive way, we analyzed CRP in different phenotypes of obesity, with precision on actual excess adiposity and the location of its accumulation." (PMID 40565915, 2025). "CRP and IL-6 are considered inflammatory biomarkers to assess the presence and severity of low-grade inflammation in obesity." (PMID 40565915, 2025). "In contrast to serum Lp(a), serum hs-CRP was higher in the simple obesity control group in comparison to the healthy control group (P = .002)." (PMID 40401233, 2025). "One potential explanation for the strongerassociation between obesity and CRP in women is the difference in fatdistribution between sexes." (PMID 40926826, 2025).
Obesity (continued). "Lower systolic blood pressure, C-reactive protein (CRP), blood glycemic parameters (glucose and insulin), lipid profile (lower triglyceride, higher HDL-C), anthropometric measurements linked obesity (waist circumference, body mass index) have been shown." (PMID 41280398, 2025). "Doses of 1 g/day did not produce significant changes in anthropometric parameters or body composition in men with obesity, but they did significantly reduce the mean values of C-reactive protein (CRP) levels, indicative of systemic inflammatory mitigation." (PMID 40733199, 2025). "CRP concentrations at 12, 28 GW increased with higher BMI (for normal weight, overweight, and obesity, respectively: 12 GW 4.12 vs 6.68 vs 11.7 mg/L, P < 0.001; 28 GW 4.45 vs 6.87 vs 9.70 mg/L, P < 0.001)." (PMID 40886951, 2025). "We constructed five comparative models to evaluate the incremental value of different obesity indices: a baseline model (f1) including age, hypertension, Sc, and CRP; and four additional models incorporating BMI (f2), WHtR (f3), TG/HDL (f4), or CMI (f5)." (PMID 40235661, 2025). "In hepatocytes, diet-induced obesity increases NF-κB signaling 2-fold, correlating with glucose intolerance through mechanisms involving hepatic C-reactive protein (CRP) production and altered adipokine secretion." (PMID 40699756, 2025). "Another study conducted in adolescents with obesity found that NLR and C-reactive protein (CRP) levels were significantly higher in the obesity group compared to healthy controls." (PMID 41374089, 2025). "Risk estimates for obesity-related and gastrointestinal cancers for low YKL-40 and high CRP combination was similar to high YKL-40 and low CRP combination." (PMID 40188292, 2025). "C-reactive protein (CRP) and fibrinogen levels increase progressively with higher obesity classes in the general population, including the elderly." (PMID 41227378, 2025). "Most obesity-related compounds in the blood are also in saliva, i.e., insulin, leptin, α-amylase, tumor necrosis factor α/interleukin 6, C-reactive protein, and adiponectin." (PMID 40565251, 2025). "CRP, in particular, showed the strongest correlation with BMI, highlighting its potential role in chronic inflammation related to obesity." (PMID 40551726, 2025). "After adjustment for age, sex, obesity, active cancer, D-dimer, CRP, and IL-6, severe lung involvement remained a strong independent predictor of in-hospital mortality (OR 4.46; 95% CI 1.55–12.86; p = 0.006)." (PMID 41463074, 2025). "In people with obesity and related comorbid conditions, IL-6 secreted from adipose tissue contributes to the production of hepatic CRP and a pro-inflammatory environment." (PMID 40805975, 2025). "A significant inverse association was reported between OF consumption and the log of C-reactive protein concentration and log of cystatin-C concentration.,23 MetS prevalence, and BMI and obesity during childhood and adulthood." (PMID 39101594, 2025). "There is abundant evidence that circulating levels of inflammatory markers, including high-sensitivity C-reactive protein (hs-CRP), interleukin-6 (IL-6), and ferritin, are significantly higher in people with obesity compared to peers of normal weight." (PMID 40868054, 2025). "Several key inflammatory markers have been reported to involve in obesity-induced inflammatory responses, including CRP, IL-6, and tumor necrosis factor-α (TNF-α)." (PMID 40568560, 2025). "In people with obesity, the levels of inflammatory markers in the blood, such as CRP and white blood cell count, are elevated." (PMID 41048699, 2025). "Among the proteins upregulated in obesity, CRP, C9, and APOC1 not only showed elevated abundance but also demonstrated strong, consistent links across metabolic, vascular, and inflammatory domains." (PMID 40981199, 2025).
Obesity (continued). "Individuals with obesity, especially those exhibiting a substantial accumulation of visceral fat, demonstrate heightened systemic levels of inflammatory markers, including C-reactive protein (CRP), various cytokines, and interleukins." (PMID 39861442, 2025). "Use of bDMARDs (β −0.22, p = 0.03) at follow-up remained associated with lower LV mass index at follow-up after adjustment for age, sex, obesity, and CRP levels in multivariable analyses." (PMID 41141372, 2025). "CRP remains the most extensively studied inflammatory marker in OSA, and prior meta-analyses and extensive cohort studies have consistently demonstrated higher CRP levels in patients with more severe disease, particularly in the presence of obesity." (PMID 41517522, 2025). "The significant reduction in CRP levels in the combined group indicates a potent attenuation of this obesity-driving inflammatory cascade." (PMID 41404432, 2025). "Adipose tissue, especially in obesity, secretes pro-inflammatory cytokines, which in turn stimulate hepatic production of CRP." (PMID 41404432, 2025). "An independent relationship was found between PTX3, hs-CRP, and different obesity-related indices in patients with preDM and T2DM." (PMID 40332236, 2025). "Pregnancy is associated with a metainflammatory state that is heightened by obesity, with primary increases in circulating interleukin 6 (IL-6) and C-reactive protein (CRP)." (PMID 40637163, 2025). "Exercise interventions (aerobic, resistance, and combined training) can significantly reduce obesity indicators including WC, BMI, and BF%, while lowering levels of inflammatory markers such as CRP, TNF-α, and IL-6." (PMID 41561801, 2025). "Chronic low-grade inflammation (CLGI), characterized by the persistent elevation of pro-inflammatory mediators such as CRP, IL-6, and TNF-α, is a defining feature of obesity-associated PCOS." (PMID 41239503, 2025). "Taken together, these studies indicate that salivary CRP is a promising marker for systemic inflammation in children and adolescents with overweight or obesity." (PMID 40547317, 2025). "Diets rich in fruits, vegetables, and plant oils—sources of phytochemicals and antioxidants—produce significant decreases in CRP among people with overweight, obesity, and diabetes." (PMID 41301434, 2025). "Research findings indicate that being overweight significantly raises the likelihood of clinically relevant increases in CRP, and this link is particularly pronounced in individuals with obesity." (PMID 40724779, 2025). "The Hisayama Study (2005) supported these findings in a Japanese cohort, highlighting CRP’s predictive role independently of obesity or insulin resistance." (PMID 40725102, 2025). "Consistent with previous research, individuals with obesity in our study exhibited significantly higher levels of CRP, insulin, and triglycerides, all of which are established markers of metabolic dysfunction and inflammation." (PMID 41374089, 2025). "Specifically, Vitamin D, AAST, Glucose, CRP, Obesity, and Weight have contributed SHAP values of +0.12, +0.05, +0.04, +0.03, +0.02, and +0.02, respectively." (PMID 40942916, 2025). "A marked difference was also observed in CRP levels between children with obesity with the AG (2.31 mg/L) and AA (4.25 mg/L) genotypes." (PMID 40722558, 2025). "The existing literature to date paints a complex and often conflicting picture of the interplay between leptin, VEGF, MPO, CRP, and microvascular function in obesity." (PMID 40900465, 2025). "While these markers offer insights into systemic inflammation and metabolic dysfunction, the MASLD criteria exclude CRP and HOMA-IR for broader applicability, focusing on universally recognized risk factors like obesity, type 2 diabetes, and dyslipidaemia." (PMID 39808219, 2025). "Another systematic review of randomized controlled trials (RCTs) in adults with obesity has also shown that DF intake is related to a reduction in CRP concentrations." (PMID 40949172, 2025).
Obesity (continued). "Our study’s observation of higher CRP and D-dimer levels in obese patients during metabolic crises aligns with the existing literature, supporting that obesity-related inflammation and thrombosis are serious contributors to acute metabolic disorders." (PMID 40002762, 2025). "Beyond its structural genomic alterations, obesity is characterised by metabolic dysfunction and chronic inflammation, documented by elevated BMI and CRP levels and leukocyte counts, alongside epigenetic dysregulation." (PMID 40429924, 2025). "Inflammatory markers such as C-reactive protein (CRP) and IL-6 are elevated in women with overweight/obesity." (PMID 40886951, 2025). "In the setting of obesity, dysfunctional adipose tissue triggers the release of pro-inflammatory cytokines, including interleukin-6, tumor necrosis factor-α, and C-reactive protein." (PMID 41415798, 2025). "BMI and CRP are also part of this factor, as obesity is one of the main risk factors for the development of insulin resistance and MASLD, while CRP is an indicator of inflammation that occurs in MASH." (PMID 40141039, 2025). "In obesity, IL-6 is released from visceral adipocytes into the portal vein and directly acts on the liver to induce the production of CRP." (PMID 40568560, 2025). "This interaction suggests that systemic inflammation as measured by CRP is not only influenced by the presence of IL-6 but is also exacerbated in the context of obesity." (PMID 41289287, 2025). "Previous studies on the relationship between hs-CRP and MetS have similarly identified obesity as a major determinant of elevated CRP levels." (PMID 40474309, 2025). "For example, in Bazzano’s RCT (12 months; adults with obesity), the reduction in (hs-)CRP was greater with a low-carbohydrate diet than with a low-fat diet (between-group Δ = −15.2 nmol/L; 95% CI: −27.6 to −1.9; p = 0.024; ≈ −1.75 mg/L)." (PMID 41305609, 2025). "Educational gradients were evident in both sexes, but they were more pronounced among females, especially regarding hypertension, overweight/obesity, central adiposity, WC, and high-sensitivity C-reactive protein (hs-CRP) levels (p-values for trend: <0.001)." (PMID 40944215, 2025). "An interesting study in rhesus monkeys reported that CRP, dopamine, and dietary habits that lead to obesity show an intriguing connection, demonstrating the complexity of living organisms." (PMID 40565981, 2025). "In conclusion, LCDs appear to modestly reduce CRP levels overall, with greater effects observed in trials lasting more than 12.5 weeks and among individuals with obesity and elevated baseline CRP concentrations (> 4.5 mg/L)." (PMID 40688603, 2025). "This scoring system integrates three laboratory indicators (hemoglobin, procalcitonin [PCT], and C-reactive protein) and three significant comorbidities (cardiac, hepatic, or renal insufficiency combined as a single parameter, immunosuppression, and obesity)." (PMID 40612051, 2025). "CRP was positively correlated with BMI, total, and truncal fat in the present study, consistent with prior literature that obesity relates to chronic inflammatory state." (PMID 40781458, 2025). "Meanwhile, meta-analyses in related conditions such as osteoarthritis and obesity demonstrate ginger’s capacity to significantly reduce c-reactive protein (CRP) and TNF-α, indirectly supporting its anti-inflammatory potential in allergy." (PMID 41305557, 2025). "For example, both models identified obesity and inflammation as central factors; however, the GS model distilled the network to emphasize that BMI and CRP influence many other nodes, with fewer secondary links." (PMID 41154955, 2025). "Obesity triggers systemic inflammation (e.g., increased CRP, IL-6, and leptin) and reduces vitamin D availability, both of which are implicated in MS development." (PMID 40909065, 2025).
Obesity (continued). "BMI-predictive proteins included established obesity markers and obesity-related proteins, including adiponectin, CRP, IGFBP1, IGFBP2, PRG4, SHBG, apolipoproteins (APOA4, APOF) and inflammatory response proteins (A2M, APCS, LBP, HSPG2, HP, AOC3, ITGB1, VNN1)." (PMID 39972214, 2025). "Chronic low-grade inflammation is a defining feature of obesity, and high levels of TNF-α and CRP are caused by several reasons, including immunological activation, metabolic abnormalities, and dysfunctional adipose tissue." (PMID 40700071, 2025). "It is believed that the increase in CRP levels in obesity is due to the rise in fat tissue and the accumulation of free fatty acids, which stimulate the release of pro-inflammatory cytokines and CRP synthesis in the liver." (PMID 40719205, 2025). "CVR factors like obesity, lipid and glucose profiles, liver fibrosis risk (FIB-4 ≥ 1.3), C-reactive protein, and family history of CVD were evaluated." (PMID 40004749, 2025). "When examined according to genotype distribution, a marked difference was also observed in CRP levels between children with obesity with the AG (2.31 mg/L) and AA (4.25 mg/L) genotypes." (PMID 40722558, 2025). "Studies report a strong association between increased CRP levels and key metabolic abnormalities in PCOS such as insulin resistance, obesity, dyslipidemia, and endothelial dysfunction." (PMID 40385768, 2025). "Although obesity is commonly thought to induce inflammation, we observed an increase in serum CRP concentration in the HFFC group 4 weeks before significant differences in BW were observed between the two diet groups." (PMID 40770069, 2025). "In contrast, Vitamin D = 12.7, ALP = 127, CRP = 0.6, and Obesity = 14.1 have produced positive SHAP values, attempting to counterbalance the misclassification." (PMID 40942916, 2025). "Previous studies have also demonstrated that several factors are associated with post-AMI NOAF, such as age, gender, obesity, HR, Killip class, BNP level, hs-CRP level, LAD, and LVEF." (PMID 41437992, 2025). "This study aims to investigate the relationship between maternal overweight, obesity, and excessive weight gain during pregnancy and high‐sensitivity C‐reactive protein (hs‐CRP), an acute‐phase reactant of inflammation and infection in maternal serum." (PMID 40329709, 2025). "The pro-inflammatory marker, C-reactive protein (CRP), is also increased in individuals with obesity compared to lean individuals." (PMID 41000378, 2025). "Obesity is associated with elevated levels of IL-6, TNF-α, CRP, and leptin, as well as altered macrophage profiles - all of which contribute to systemic and neural inflammation." (PMID 40909065, 2025). "Together, these findings highlight the need to integrate CNVs profiling with epigenetic and inflammatory biomarkers (such as CRP and methylation status) to improve patient stratification and personalise obesity management strategies." (PMID 40429924, 2025). "In cases of obesity, adipose tissue releases pro-inflammatory cytokines such as TNF-α, IL-6, and CRP, which play a role in causing liver inflammation and injury." (PMID 41007669, 2025). "The CRP > 2 mg/L group displayed more unhealthy lifestyle traits, including obesity, increased consumption of processed meats, lower intake of fruits and vegetables, lack of physical activity, and a higher prevalence of smoking." (PMID 41387931, 2025). "In the study, we found that CRP levels were significantly higher in the children with obesity (4.14 mg/L) compared to the healthy controls (1.99 mg/L) (p = 0.008)." (PMID 40722558, 2025). "When the analysis was adjusted for age, sex, smoking, 25(OH)D, and vitamin D intake, hs-CRP was found to be significantly higher in the obesity group compared to the comparator group (p = 0.044)." (PMID 40868054, 2025). "Higher mean levels of IL-6 and CRP were observed in the BMI ≥ 25 group, indicating an elevated inflammatory response in individuals with overweight or obesity." (PMID 40944273, 2025).